IRF8 (interferon regulatory factor 8)
Diseases named in the same sentence as IRF8 in open-access papers (continued):
Sharing a sentence is not in itself a finding about the gene and the disease.
tumor (continued). "Correspondingly, high expression of IRF8 was associated with longer OS and may be related to inhibition of migration and invasion by inducing tumor cell cycle arrest and apoptosis." (PMID 34795691, 2021). "Also, consistent with the role of IRF8 as a tumor suppressor, high expression of IRF8 has been significantly associated with longer overall survival in ER-negative BC." (PMID 33766090, 2021). "In the context of the development of BL, an acquired activating mutation in IRF8 may compensate for the loss of EBNA3C in tumor cells." (PMID 33505922, 2020). "Furthermore, differential gene expression analyses revealed that IRF8-deficient myeloid cells displayed a gene expression profile that resembled tumor-induced PMN-MDSCs significantly more so compared to those of the non-tumor-bearing controls." (PMID 32983128, 2020). "Consequently, to gain broader insights into the molecular basis for this IRF8-dependent tumor growth advantage, we performed preliminary microarray studies using the IRF8-expressing/IRF8-deficient CMS4 mouse isogenic tumor pair." (PMID 26008967, 2015). "To test our central hypothesis, we focused on two questions: 1) Is IRF-8 expression in tumor cells required for their susceptibility to Fas-mediated killing induced by HDACi?" (PMID 23028998, 2012). "To test this hypothesis, we investigated the effects of TSA treatment in mice bearing either IRF8-competent (CMS4) or IRF8-deficient (CMS4-shRNA) tumor cells." (PMID 23028998, 2012). "Furthermore, a number of interferon (IFN) response genes (BST2, CD74, HLA-DMA, HLA-DPB1, HLA-DQB1, HLA-DRA, HLA-DRB1, and IRF8) were upregulated in C10 compared to the other clusters, whereas genes associated with tumor suppression and apoptosis (TFF1 and TFF2) were downregulated." (PMID 37370788, 2023). "Moreover, when we used TCGA data combined with MIXTURE, an immune tumor microenvironment estimation method based on gene expression data, we validated again that IRF8 expression was associated with a relatively more abundant CD8+ T cell infiltration in ER-negative, HER2+, and TNBC subtypes." (PMID 33766090, 2021). "Finally, the deficiency of IRF8 in Th9 cells impairs their anti-tumour properties." (PMID 29233972, 2017). "Therefore, high IRF8 expression associated with unfavorable survival may be related to the suppression of IL-17 expression in the tumor microenvironment." (PMID 28537908, 2017). "Furthermore, we and others have now found that IRF8 can be expressed, but typically is epigenetically silenced in non-hematopoietic malignancies or repressed by immune-associated soluble factors during tumor-induced alterations in myelopoiesis." (PMID 26008967, 2015). "Thus, IRF8 was initially implicated as a ‘tumor suppressor gene’ in certain hematopoietic cancers." (PMID 26008967, 2015). "An NR1H2 cluster expressing IRF8 was identified on the metastatic tumor samples isolated from the peritoneum." (PMID 41601649, 2026). "IRF8-expressing TAMs contribute to tumor-reactive cytotoxic T lymphocyte (CTL) exhaustion by presenting tumor antigens and inducing PD-1 expression on CD8+ T cells." (PMID 41596598, 2026). "Our findings revealed a higher abundance of TLSs in tumor tissue with a low abundance of LAMP3+ IRF8 + DCs compared to tumor tissue with a high abundance of LAMP3+ IRF8 + DCs." (PMID 41190765, 2026). "These SEs are believed to drive the overexpression of RARA or IRF8 genes, leading to tumor development by targeting immature, undifferentiated, and proliferating cells." (PMID 40672386, 2025). "IRF8 is a kind of interferon regulatory transcription factor, playing a crucial role in tumorigenesis, tumor development, and immune responses." (PMID 39940857, 2025). "After 30 days, both tumor volume and tumor weight were reduced in the dox-induced IRF8 overexpression group compared to the vector." (PMID 39940857, 2025).
tumor (continued). "IRF8 is a key transcription factor that plays roles in macrophage development, can act as a tumor suppressor, and function to regulate inflammatory signaling." (PMID 40345583, 2025). "In stark contrast to its pro-cancer role in CSCs, IRF8 consistently functions as a tumor suppressor in differentiated and mature common cancer cells." (PMID 41368628, 2025). "This indicated that IRF8 overexpression dramatically inhibited tumor progression and metastatic nodule numbers." (PMID 39940857, 2025). "On the basis of the correlation between IRF8 expression and GC outcomes, we next considered the impact of IRF8 expression on tumor growth in different GC mouse models." (PMID 39940857, 2025). "The results showed that tumor growth from the mice bearing IRF8-overexpressing cells was significantly inhibited after anti-PD-1 treatment." (PMID 39940857, 2025). "In preclinical GBM models, therapeutic approaches that boost Irf8 activity, such as gene therapy utilizing retroviral replicating vectors, have shown decreased immunosuppression and decreased tumor development." (PMID 40564171, 2025). "In the context of tumor immunity, IRF-8 enhances the presentation of tumor antigens by promoting T cell activation and fostering a robust anti-tumor immune response." (PMID 41315179, 2025). "Interferon regulatory factor 8 (IRF8) is a transcription factor required for the ability of M2 TAMs to present antigens to tumor cells." (PMID 40649751, 2025). "Our study reveals that IRF-8 exerts a tumor suppressive role in neoplastic cells, wherein the reinstatement of IRF-8 through TRIM63 abrogation elicits diverse cellular processes leading to tumor cell eradication." (PMID 41315179, 2025). "In summary, the findings from our data analysis suggest that the regulatory axis of TRIM63/IRF-8 plays a significant role in promoting tumor progression, both within tumor cells and the immune microenvironment." (PMID 41315179, 2025). "Among these genes, IRF8 and TOX2 encode for transcription factors involved in immune cell regulation and development, with IRF8 playing a tumor suppressor role in AML and TOX2 being involved in regulation of T-cell response in CLL." (PMID 40456839, 2025). "IRF8 exhibits functional heterogeneity during tumorigenesis, demonstrating varying roles across different tumor cell populations." (PMID 41368628, 2025). "In murine tumor models, IRF8 levels regulate the size of peripheral MDSC pools, particularly PMN-MDSCs, without affecting the immunosuppressive functionality of the remaining MDSCs." (PMID 41368628, 2025). "The percentage of mutations in the genes was below 5% in a variety of tumours, except in DLBC where the frequency of mutations in IRF4 and IRF8 was 14% and 8%." (PMID 38130025, 2024). "Interferon regulatory factor 8 (IRF8) in tumor cells and in CD11b + Ly6CloLy6G+ myeloid cells has been found to be a suppressor of Opn." (PMID 39272810, 2024). "PDAC tumour cells can also inhibit development of dendritic cells by release of granulocyte colony stimulating factor (G‐CSF), which inhibits IRF8‐mediated development of dendritic cells in the bone marrow." (PMID 38426634, 2024). "Both myeloid and tumor cells strategically exploit the suppression of IRF8 expression to enhance OPN levels." (PMID 38646539, 2024). "While during PDAC progression, tumor-produced CSF3 down-regulated interferon regulatory factor-8 (IRF8) in cDC progenitors, leading to slower cDC1 development and reduced numbers." (PMID 38167055, 2024). "Here, we developed an approach to reprogram tumor cells in vivo by adenoviral delivery of the transcription factors PU.1, IRF8, and BATF3, which enabled them to present antigens as type 1 conventional dendritic cells." (PMID 39236156, 2024). "Given conserved roles for Irf8 across species in the specification and function of different phagocyte populations, our functional data suggested an anti-tumor role for irf/phagocyte activity in the TME during p53EPS tumor initiation." (PMID 39052000, 2024).
tumor (continued). "This anti-tumor role is further supported by our functional analyses showing increased p53EPS tumor initiation in the context of Irf8 gene knock-out and decreased phagocytic cell development in vivo in zebrafish larvae." (PMID 39052000, 2024). "IRF4 and IRF8 contributed to tumor immunity by modulating the functions of T cells, B cells, and NK cells." (PMID 38999981, 2024). "IRF-8 is a key transcription factor that regulates macrophage differentiation and activation and that plays a tumor suppressor role." (PMID 37205092, 2023). "Although IRF8 deficiency alters DC and macrophage compartment in TIME, strategies to overexpress IRF8 in TAMs and DCs should be carefully used depending on the tumor type and their TIME." (PMID 37380989, 2023). "IRF8 mutant CMS4.K79E cells exhibited decreased sensitivity to 2/20 CTL-induced cell killing as compared to the vector control cells, indicating that IRF8 regulates 2/20 CTL-induced tumor cell death." (PMID 36672246, 2023). "To establish IRF8-deficent tumor cells lines, we treated IRF8 knock-out mice and wild-type (WT) C57BL/6 mice with the carcinogen methylcholanthrene (MCA)." (PMID 36672246, 2023). "IRF8 functions as a tumor suppressor, its function, at least in part, depending on its function in the regulation of tumor cell apoptosis." (PMID 36672246, 2023). "One of the repressive transcriptional targets of IRF8 is AC; consequently, as IRF8 is lost, AC expression increases, solidifying its role as a tumor suppressor." (PMID 37760612, 2023). "A comparison of IRF8 expression level in tumor cells between patients who responded to nivolumab and patients who did not determined that the IRF8 expression level is significantly higher in the responders than in the non-responders." (PMID 36672246, 2023). "The WT and IRF8.KO tumor cells were treated with erastin and RSL3, respectively, and analyzed for cell death." (PMID 36672246, 2023). "Lastly, CD8EX cells in C12 exhibited high expression of Irf8 and Spp1 that in 4T1 tumors have been associated with balancing generation of antigen-specific CD8+ T cells and tumor rejection." (PMID 37620372, 2023). "It is, therefore, likely that IRF8 is upregulated in tumor cells by activated CTLs in the tumor microenvironment." (PMID 36672246, 2023). "We then used the CMS4 tumor cell lines stably expressing an IRF8 dominant-negative mutant (CMS4.K79E)." (PMID 36672246, 2023). "Restoring IRF8 expression via a lipid nanoparticle-encapsulated NTC9385R-mIRF8 plasmid therapy suppressed established tumor growth in vivo." (PMID 36672246, 2023). "Taken together, our observations indicate that IRF8 regulates target tumor cell sensitivity to ferroptosis induction by tumor-specific CTLs." (PMID 36672246, 2023).
tumor (continued). "Consistent with sensitivity to ferroptosis induction by RSL3, the WT tumor cell lines exhibit a higher lipid ROS level than the IRF8 KO tumor cell lines." (PMID 36672246, 2023). "Genome-wide gene expression profiling identified the ferroptosis pathway as an IRF8-regulated pathway in tumor cells." (PMID 36672246, 2023). "IRF8 has been identified as a tumor suppressor in AML, and when IRF8 is removed from mice the animals develop a spontaneous disease with similarities to human CML, including a transition to blast crisis in about a third of animals." (PMID 36969082, 2023). "Here, we report that interferon regulatory factor 8 (IRF8) functions as a regulator of tumor cell intrinsic ferroptosis." (PMID 36672246, 2023). "Abnormal silencing of IRF8 is involved in various tumors and hematological malignancies, highlighting its role as a tumor suppressor gene." (PMID 36478193, 2023). "In this report, we systematically review the precise roles of IL-9, IRF-8, and AP-1 in tumor development, particularly with regard to DLBCL." (PMID 35211408, 2022). "Analysis of human lung tumor specimens at the single cell level validate the early finding that IRF8 is silenced in the tumor cells." (PMID 36078039, 2022). "Expression of tumor suppressor genes inhibited lens cell carcinoma growth upon transfection with IRF8." (PMID 36078039, 2022). "DAC treatment stimulates the Irf8 promoter demethylation and expand IRF8+MDSCs in tumor microenvironment." (PMID 36439186, 2022). "Further supporting MDSC suppression by IRF8, IRF8-deficient mice generated MDSC-like populations highly homologous to tumor-induced MDSCs while IRF8 overexpression attenuated MDSC accumulation." (PMID 36078039, 2022). "IRF8 is now known to play a key role in epithelial cell turnover and functions as a tumor suppressor in solid tumors." (PMID 36078039, 2022). "Genes previously associated with cDC1, including CLEC9A, XCR1, CADM1, TBHD and IRF8 are conserved across multiple tumor types." (PMID 36230990, 2022). "In certain types of cancers, IRF8 functions as a tumor suppressor gene, and its expression is regulated by DNA methylation or micro-RNA interference." (PMID 36078039, 2022). "Immature DCs incubated with primary oral squamous cell carcinoma cell lines show significantly lower expression of several MHC class I processing components like MB1 (β5), LMP2,7,10, and ERp57, induced by tumor derived ganglioside or IRF-8." (PMID 36230990, 2022). "IRF8 silencing by its promoter DNA methylation leads to accumulation of MDSCs in both human cancer patients and tumor-bearing mice." (PMID 36078039, 2022). "Even if IRF8 is mainly expressed in the nuclei of tumor cells, weak IRF8 expression in cytoplasm was also detectable." (PMID 33766090, 2021). "Less is known regarding the role of IRF8 in BC cells, but reports are consistent with a tumor suppressive role." (PMID 33766090, 2021). "IRF8 has previously been described as a tumor suppressor, while our data suggest an oncogenic function in AML." (PMID 33673123, 2021). "Another member, IRF8, was also down-regulated in colorectal and BC tumor tissues, involved in antigen capture and response to interferon." (PMID 34795691, 2021). "In contrast, only 34% of the grade 3 (G3) or poorly differentiated tumor samples exhibited high IRF8 expression." (PMID 33766090, 2021). "Accordingly, IRF8 has been found to act as tumor suppressor in other solid tumors and hematopoietic malignancies." (PMID 33766090, 2021). "Importantly, these tumor-derived GPs were shown to mirror the transcriptional profile of GPs isolated from IRF8−/− mice compared to those of the non-tumor-bearing controls, lending further evidence that the loss of IRF8 expression during granulopoieses skews myeloid differentiation toward PMN-MDSCs." (PMID 32983128, 2020).
tumor (continued). "Notch1 expression was also increased and Ikaros/IRF8 expression decreased in the DN2 population isolated from tumor-bearing IL-10−/− mice as compared to wild-type tumor-bearing mice." (PMID 32582141, 2020). "Taken together, these data indicate that hetIL-15 treatment promotes the production of the chemokine XCL1 by intratumoral lymphocytes leading to increased tumor infiltration by CD103+XCR1+IRF8+ cDC1." (PMID 32461349, 2020). "A central finding from our study is that IRF8 was downregulated in tumor-infiltrate CD8+ exhausted T cells compared to adjacent normal tissues." (PMID 32039830, 2020). "The transcription factor IRF8 was found concomitantly significantly hypermethylated and downregulated, which is significant given its function as a tumor suppressor and its frequent downregulation in various cancer types through epigenetic silencing." (PMID 32737342, 2020). "Tumor-driven downregulation of IRF8 was found to dysregulate myelopoiesis at least in part by promoting the expansion of tumor-derived GPs, which selectively led to PMN-MDSCs." (PMID 32983128, 2020). "Downregulation of interferon regulatory factor-8 (IRF-8) has emerged as a tumor mediated event that can lead to the accumulation of MDSCs." (PMID 33203146, 2020). "High OPN expression induced by interferon regulatory factor 8 downregulation in tumor cells was found to suppress the activation of CD8 cells by binding to their CD44 receptors." (PMID 33187327, 2020). "We assessed the expression of the interferon regulatory factor 8 (IRF8) transcription factor in tumor-infiltrate CD8+ exhausted T cells and CD8+ TILs from 11 GC patient tumors and found that IRF8 was downregulated in both compared to normal tissues." (PMID 32039830, 2020). "Focusing on the peripheral, differentiated cDC populations, we next assessed protein expression of the IRF8 transcription factor in tumor-derived cDC populations." (PMID 33268774, 2020). "Subsequently, DNMT1 and DNMT3b proteins hyper-methylate the promotor region of the anti-tumour gene irf8 resulting in interferon regulatory factor 8 (IRF8) protein downregulation." (PMID 32931721, 2020). "The CRISPR knockout screen also identified IRF8, a transcription factor that is thought to function as a regulator of apoptosis and potentially acts as a tumor suppressor." (PMID 33505922, 2020). "As the cytokine microenvironment within the thymus critically regulates T-cell development and is perturbed by tumor conditioning, we assessed cytokines for their role(s) in reciprocally regulating Notch1 and Ikaros/IRF8 expression in arrested T cells." (PMID 32582141, 2020). "A significantly higher percentage of the CD68+CD206+ and the CD68+IRF8+ macrophages had tumor cells within a 10 μm radius (median effective percentages of 31 and 27%, respectively)." (PMID 31477692, 2019). "The majority of the CD68+IRF8+ macrophages (78%) had tumor cells within 20 μm radius of their nucleus." (PMID 31477692, 2019). "In contrast, CD68+IRF8+ macrophages, were more abundant in the core compared with the margin, and were located within the tumor-nest than in the stroma." (PMID 31477692, 2019). "IRF8 expression is also negatively correlated with metastatic potential by increasing tumor resistance to Fas-mediated apoptosis." (PMID 31684858, 2019). "In summary, we report that macrophage expression of IRF8 is inversely correlated with tumor mass and directly related to survival outcome." (PMID 31221219, 2019). "Mechanistically, tumor-produced granulocyte-stimulating factor downregulates interferon regulatory factor-8 in cDC progenitors, and thus results in reduced cDC1 development." (PMID 29593283, 2018). "In support of this notion, our expression profiling demonstrated that Irf8 messenger RNA (mRNA) was downregulated in cDC progenitors from tumor-bearing mice." (PMID 29593283, 2018).